CITED1 (Cbp/p300 interacting transactivator with ED-rich tail 1)
Description:
Transcriptional coactivator of the p300/CBP-mediated transcription complex. Enhances SMAD-mediated transcription by strengthening the functional link between the DNA-binding SMAD transcription factors and the p300/CBP transcription coactivator complex. Stimulates estrogen-dependent transactivation activity mediated by estrogen receptors signaling; stabilizes the interaction of estrogen receptor ESR1 and histone acetyltransferase EP300. Positively regulates TGF-beta signaling through its association with the SMAD/p300/CBP-mediated transcriptional coactivator complex. Induces transcription from estrogen-responsive promoters and protection against cell death. Potentiates EGR2-mediated transcriptional activation activity from the ERBB2 promoter. Acts as an inhibitor of osteoblastic mineralization through a cAMP-dependent parathyroid hormone receptor signaling. May play a role in pigmentation of melanocytes. Associates with chromatin to the estrogen-responsive TGF-alpha promoter region in a estrogen-dependent manner.
Synonyms: MSG1
Tractability: No criterion of Open Targets' tractability assessment is met for any kind of drug.
Gene: Protein-coding gene on chromosome X (72,301,638 to 72,309,652, reverse strand). Ensembl gene ENSG00000125931.
Subcellular location: Nucleus; Cytoplasm
Subcellular location (Human Protein Atlas): Nucleoplasm; Cytosol
Pathways (Reactome):
Gene expression (Transcription): Activation of the TFAP2 (AP-2) family of transcription factors
Signal Transduction: Estrogen-dependent gene expression
Gene Ontology:
Molecular function: co-SMAD binding; LBD domain binding; protein binding; protein homodimerization activity; transcription coactivator activity; chromatin binding
Biological process: melanocyte differentiation; negative regulation of DNA-templated transcription; negative regulation of neuron apoptotic process; nucleocytoplasmic transport; pigmentation; positive regulation of DNA-templated transcription; positive regulation of transcription by RNA polymerase II; regulation of apoptotic process; response to estrogen; response to transforming growth factor beta; SMAD protein signal transduction; transforming growth factor beta receptor signaling pathway; branching involved in ureteric bud morphogenesis; melanin biosynthetic process; mesenchymal to epithelial transition; metanephros development; negative regulation of osteoblast differentiation; negative regulation of Wnt signaling pathway; placenta development; positive regulation of gene expression; positive regulation of mesenchymal stem cell proliferation; positive regulation of transforming growth factor beta receptor signaling pathway; regulation of transcription by RNA polymerase II; response to cAMP; response to cytokine; and 12 more
Cellular component: cytoplasm; cytosol; nucleoplasm; nucleus
Homologues: Orthologues: chimpanzee CITED1 (99% identical), pig CITED1 (93% identical), dog CITED1 (91% identical), rat Cited1 (81% identical), mouse Cited1 (78% identical), zebrafish cited1 (38% identical). Paralogues in human: CITED2 (36% identical), CITED4 (26% identical).
Diseases named in the same sentence as CITED1 in open-access papers:
CITED1 is named in the same sentence as 37 diseases in open-access papers, as found by Europe PMC text mining. Sharing a sentence is not in itself a finding about the gene and the disease. The quoted sentences say what the papers report.
melanoma (17 papers, 2007 to 2024). A malignant, usually aggressive tumor composed of atypical, neoplastic melanocytes. "We tested the association between cell morphology and nuclear CITED1 using the panel of 16 human melanoma cell lines." (PMID 26526369, 2015). "Deregulation of CITED1 has been implicated in several human cancers, including melanomas, Wilm's tumours and nephroblastomas." (PMID 23935526, 2013). "Moreover, CITED1 is highly upregulated during melanoma progression, and its high expression is associated with poor prognosis." (PMID 26526369, 2015). "TGF-β upregulated the contractile actomyosin cytoskeleton in melanoma through SMAD/CITED1-driven transcription." (PMID 39222238, 2024). "CITED1 expression was also shown in adult heart and mammary gland, melanocytes, melanoma cells, and papillary thyroid carcinoma." (PMID 38997708, 2024). "CDKN1C suppression following CITED1 overexpression has been shown to augment cell cycle progression and cell viability in melanoma cells." (PMID 32015692, 2020). "CITED1 is the most well-studied in melanoma progression that can be activated by the TGFβ-SMAD2 pathway and promote amoeboid migration of melanoma cells." (PMID 31296175, 2019). "CITED1, formally known as MSG1, was first isolated in 1996 from murine melanoma B16-F1 cells and mapped to chromosome Xq13.1 in humans." (PMID 29559927, 2018). "Downstream of TGFβ, SMAD2 and its adaptor CITED1 regulate the amoeboidal characteristic of melanoma cells." (PMID 28137308, 2017). "We then analyzed a smaller cohort of melanoma patients (“English” cohort) for a more detailed analysis of CITED1 localization." (PMID 26526369, 2015). "We subsequently interrogated the gene expression data on the primary melanoma lesions using a nearest centroid approach derived from the CITED1-silenced gene signature." (PMID 25755924, 2015). "As the tumour subtype classification was shown to be prognostically significant in primary melanomas we were interested to know if CITED1 expression itself was independently predictive of outcome." (PMID 25755924, 2015). "To investigate the effect of CITED1 silencing on melanoma cells behaviour we analysed the cell cycle distribution following siRNA treatment by flow cytometry." (PMID 25755924, 2015). "CITED1 was shown to be epigenetically regulated by B-RAFV600E in tumors such as melanoma and thyroid cancer." (PMID 26526369, 2015). "On the other hand, melanomas with rounded cells in the tumor body displayed significantly higher levels of CITED1 when compared with tumors with elongated cells in the tumor body." (PMID 26526369, 2015). "Melanoma cells with intrinsically high levels of CITED1—such as A375M2—invaded efficiently in a 3D collagen matrix but displayed impaired invasion after pre-treatment with the TGF-βRI inhibitor SB431542." (PMID 26526369, 2015). "In the current study, we used melanoma cell lines harboring mutations in B-RAF or N-RAS, and we only found a correlation between CITED1 nuclear levels and actomyosin contractility, independently of genetic background." (PMID 26526369, 2015). "We verified these results using WM1361 and WM793B melanoma cell lines and using several oligonucleotides against CITED1." (PMID 26526369, 2015). "CITED1 is coupled to a contractile-rounded, amoeboid phenotype in a panel of 16 melanoma cell lines, in mouse melanoma xenografts, and in 47 human melanoma patients." (PMID 26526369, 2015). "Examination of publically available gene expression data on 120 melanoma cell lines demonstrated a consistent positive correlation between CITED1 and MITF expression (r = 0.6543)." (PMID 25755924, 2015). "This suggests that TGF-β/CITED1-driven transcription is required for melanoma interactions with the vasculature, a crucial step in extravasation." (PMID 26526369, 2015). "The role CITED1 plays in driving pro-metastatic behavior makes it an ideal candidate as a target for pharmacological intervention in melanoma." (PMID 26526369, 2015).
melanoma (continued). "To investigate the function of CITED1 in melanoma, we transiently downregulated its expression using CITED1 targeting siRNA." (PMID 25755924, 2015). "Since the functional role of CITED1 in melanoma is unclear, we decided to further investigate its connection to TGF-β-SMAD2-driven transcription." (PMID 26526369, 2015). "As we found that CITED1 highly expressed in metastatic samples, we confirmed its functional role in supporting melanoma metastasis." (PMID 26526369, 2015). "All these data show how TGF-β promotes actomyosin contractility in melanoma through increasing transcription a set of genes in a CITED1-dependent manner." (PMID 26526369, 2015). "Genes such as KRT14, GJA1, S100A7, S100A9, and EHF were higher in most melanomas while genes such as CITED-1, GDF15, QPRT, OCA2, c-MET and MME were more highly expressed in NHEM." (PMID 18442402, 2008). "Targeting CITED1 is a potential therapeutic strategy for melanoma." (PMID 39222238, 2024). "We hypothesise that the role of CITED1 in melanoma is to maintain levels of MITF compatible with tumour progression and effectively tip the balance in favour of cell cycle progression rather than MITF-induced G1-arrest." (PMID 25755924, 2015). "Accepting the caveat that we depend here on a proxy gene-signature, these data indirectly imply that CITED1 expression is a potential prognostic indicator in primary melanomas and the transcriptional program influenced by CITED1 expression determines tumour behaviour in vivo." (PMID 25755924, 2015). "We then investigated whether CITED1 was required for TGF-β/SMAD-driven transcriptional activation in melanoma." (PMID 26526369, 2015). "This indicates that CITED1 levels may be the rate-limiting step directing specific activities of the TGF-β-SMAD transcriptional complex in melanoma." (PMID 26526369, 2015). "Interestingly, even in untreated A375P cells with low basal levels of TGF-β signaling, CITED1 deletion had a marked effect on lung colonization and melanoma adhesion to endothelia." (PMID 26526369, 2015). "We next hypothesized that TGF-β could control actomyosin force in melanoma through SMAD2/CITED1-mediated transcription." (PMID 26526369, 2015). "This suggests that the adaptor CITED1 plays a very specific role in melanoma." (PMID 26526369, 2015). "In this study, we characterise the role of CITED1 as a novel regulator of MITF in melanoma." (PMID 25755924, 2015). "CITED1 is therefore required to sustain actomyosin cytoskeletal activity in melanoma cells." (PMID 26526369, 2015). "Cited1 was originally identified in a mouse melanoma cell line." (PMID 23935526, 2013). "CITED1 was originally identified in a murine melanoma cell line and in human thyroid carcinoma." (PMID 23166672, 2012). "This revealed that primary melanomas with a gene expression signature most similar to the CITED1-silenced signature (CITED1low-class) had a significantly better outcome than those with a signature most disparate from the CITED1-silenced signature (CITED1high-class)." (PMID 25755924, 2015). "Additionally, we could predict survival outcome by classifying primary melanoma tumours using our in vitro derived ‘CITED1-silenced’ gene expression signature." (PMID 25755924, 2015). "While TGFβ is known to promote EMT99 in epithelial cancers, in melanoma TGFβ signals through SMAD2 and the adaptor CITED1 to support contractile amoeboid migration." (PMID 27158478, 2016). "In order to understand the clinical significance of the TGF-β transcriptional network in malignant melanoma, we analyzed expression levels of the SMADs (SMAD1–5) and of the adaptor CITED1." (PMID 26526369, 2015). "In agreement, CITED1 positively correlates with MITF expression and can discriminate the MITF-high/pigmentation tumour molecular subtype in a large cohort of melanoma cell lines." (PMID 25755924, 2015).
melanoma (continued). "Since SMAD/CITED1 complexes act downstream of TGF-β signaling, we treated A375P melanoma cells with TGF-β in an attempt to rescue the induced amoeboid phenotype using RNAi against CITED1." (PMID 26526369, 2015). "Other identified genes, such as Cbp/p300-interacting transactivator (CITED-1), hepatocyte growth factor receptor (c-MET), and various homeobox genes have yet to be investigated in melanoma although some have been previously identified in metastatic melanoma." (PMID 18442402, 2008). "CITED1 is the central member of the CITED family of transcriptional co-regulators and was originally cloned from a differential display screen between pigmented mouse B16 melanoma cells and their dedifferentiated weakly pigmented derivative, B16F10 cells." (PMID 30450190, 2018). "Interestingly, the most upregulated gene was the adaptor CITED1, while the other adaptor SMIF was downregulated in some melanoma stages." (PMID 26526369, 2015). "CITED1 is a non-DNA binding transcriptional co-regulator whose expression can distinguish the ‘proliferative’ from ‘invasive’ signature in the phenotype-switching model of melanoma." (PMID 25755924, 2015).
Wilms tumor (6 papers, 2013 to 2024). An embryonal neoplasm characterized by the presence of epithelial, mesenchymal, and blastema components. "Cluster 2 showed expression of the nephron progenitor markers SIX1, SIX2 and CITED1, as well as the stromal marker PAX3 that has previously been associated with myogenic Wilms' tumours." (PMID 30846463, 2019). "Additionally, Cited1-transfected cells had significantly enhanced cell growth rates, in line with previous reports in Wilms’ tumor and intestinal tumor cells." (PMID 30206204, 2018). "CITED1 confers stemness to Wilms tumor and enhances tumorigenic responses." (PMID 30466390, 2018).
Obesity (4 papers, 2014 to 2025). Accumulation of substantial excess body fat. "Sex hormone estradiol modulates leptin sensitivity to control feeding and sexual dimorphism in diet-induced obesity via hypothalamic Cited1, while sex hormone receptors transcriptionally regulate sexually dimorphic gene expression." (PMID 40004248, 2025). "A total of 175 genes including thermogenic markers (UCP2, CKMT2, and CITED1) and 5 BATLAS markers (PPARGC1B, ACO2, ACSF2, NNAT, and DMRT2) were expressed less in active beige adipocytes carrying FTO obesity-risk variant as compared to risk-free carriers." (PMID 37416800, 2023).
papillary thyroid cancer (4 papers, 2018 to 2021). "It has been reported that CBP/p300-Interacting Transactivator with glutamic acid [E]/aspartic acid [D]-rich C-terminal domain 1 (CITED1) is overexpressed in papillary thyroid cancer (PTC)." (PMID 30450190, 2018). "Sassa et al35 revealed that pharmacological inhibition of methylation in TPC‐1 cells by 5‐Aza resulted in increased expression of CITED1, thereby influencing papillary thyroid cancer progression." (PMID 30039914, 2018). "In papillary carcinoma (PTC), CITED1-meditaed interference of p21 and p27 expression can increase the level of phosphorylated Rb and the transcriptional activity of E2F1, which leads to PTC cell proliferation." (PMID 33987018, 2021).
thyroid cancer (4 papers, 2012 to 2024). "A study examined the potential role of CITED1 in different malignant tumors of thyroid gland." (PMID 38997708, 2024). "Initially, we analyzed the expression of CITED1 in 59 pairs of thyroid tumor specimens and corresponding adjacent noncancerous thyroid tissues using the thyroid cancer RNAseq data deposited in the TCGA." (PMID 30450190, 2018).
colorectal cancer (3 papers, 2013 to 2017). A primary or metastatic malignant neoplasm that affects the colon or rectum. "We show that CITED1 is upregulated in human colorectal cancers and that Cited1 deficiency increases the survival of ApcMin/+ mice." (PMID 23935526, 2013). "We next assessed Cited1 levels in adenomas developing in the ApcMin/+ mouse model of human colorectal cancer, which allows evaluation of the effects of loss of Apc function over the course of polyp development." (PMID 23935526, 2013). "In particular, the expression of CITED1 is correlated with lymph node metastasis in patients with colorectal cancer." (PMID 28678795, 2017). "In colorectal cancer, CITED1 is overexpressed in human and mouse (APCmin/+ mouse model) colorectal tumors." (PMID 26243458, 2016).
breast carcinoma (2 papers, 2023 to 2024). "They proposed CITED1 could be a candidate for its potential diagnostic marker in breast cancer." (PMID 38997708, 2024). "To do this, we examined CITED1 mRNA and protein expression, in human breast cancer cell lines as well as several independent tumour datasets." (PMID 37322548, 2023). "We wanted to examine if ERα-AREG signalling is also CITED1-mediated in breast cancer cells and the relatively low levels of CITED1 in MCF7s compared to other luminal-types made them ideal for development of a CITED1-overexpression model." (PMID 37322548, 2023). "We hypothesise however, that in luminal-type/ER+/LN− breast cancer, AREG expression downstream of ERα-CITED1 may be associated with an active ERα-coregulator complex that is more amenable to endocrine antagonism." (PMID 37322548, 2023). "We hypothesised that maintenance of the ERα-CITED1 signalling pathway was indicative of a more normally functioning epithelium and subsequently showed that CITED1 correlated with better breast cancer prognosis in a tumour dataset." (PMID 37322548, 2023). "to confirm our hypothesis that CITED1 could affect ERα target genes in human breast cancer cells." (PMID 37322548, 2023).
colorectal tumors (2 papers, 2013 to 2016). "Here, we show that after Apc loss, the expression of another gene, Cited1, is increased in mice and human colorectal tumours." (PMID 23935526, 2013). "To determine if CITED1 was also deregulated in human cancers, we performed a Taqman quantitative PCR on human colorectal tumour tissues." (PMID 23935526, 2013). "Here, we have extended those observations and find that CITED1 is significantly up-regulated in colorectal tumours from patients and in intestinal adenomas developing in the ApcMin/+ mouse model." (PMID 23935526, 2013).
intestinal tumor (2 papers, 2013 to 2018). "Together, these data demonstrate that Cited1 deficiency further exacerbates both the proliferation and migration phenotypes of Apc loss in the intestine, which is surprising given that ApcMin/+Cited1− mice developed significantly less intestinal tumours than ApcMin/+mice." (PMID 23935526, 2013). "We observed that MinCited1 mice developed fewer intestinal tumours and lived longer than Min mice suggesting that Cited1 is pro-tumourigenic." (PMID 23935526, 2013).
lymph node metastasis (2 papers, 2017 to 2022). "The previous reports also stated that CITED1 is correlated with lymph node metastasis in CRC patients, suggesting that it may be used to predict the presence of lymph node metastasis." (PMID 35664306, 2022).
adenoma (1 paper, 2013). A neoplasm arising from the epithelium. "Our current primary hypothesis is that Cited1 deficiency mediates its effects upon adenoma formation primarily through the apparently paradoxical derepression of the Wnt pathway." (PMID 23935526, 2013).
bowel cancer (1 paper, 2013). "To study the role of Cited1 in bowel cancer after loss of Apc, we generated mice mutant for Apc (Min) or mutant for Apc and Cited1 (MinCited1)." (PMID 23935526, 2013).
colonic tumors (1 paper, 2013). "As Cited1 is upregulated in colonic tumors we next asked whether deficiency of Cited1 could inhibit intestinal adenoma formation in the ApcMin/+ mouse." (PMID 23935526, 2013).
cyst (1 paper, 2024). A sac-like closed membranous structure that may be empty or contain fluid or amorphous material. "Higher expression levels of CITED1, especially in keratocysts, may indicate a more specific molecular signature associated with this type of cyst, facilitating more accurate and specific diagnoses." (PMID 38997708, 2024). "As a prognostic marker, the observation of elevated CITED1 expression in certain cyst types, such as keratocysts, which are known for their aggressive behavior and recurrence, suggests a potential prognostic value." (PMID 38997708, 2024). "Although PPI network provided predicted CITED1 interactors through bioinformatic analyses, further research is needed to elucidate the mechanistic pathways through which CITEDs may contribute to cyst development and progression." (PMID 38997708, 2024). "We suggest that CITED1 could serve as a potential molecular marker for distinguishing between these cyst types." (PMID 38997708, 2024). "As a prognostic marker, the differential expression of CITED1 among these cyst types suggests that CITED1 immunohistochemistry could help in distinguishing between different types of odontogenic cysts." (PMID 38997708, 2024).